PGR (progesterone receptor)
Diseases named in the same sentence as PGR in open-access papers (continued):
Sharing a sentence is not in itself a finding about the gene and the disease.
breast cancer (continued). "IHC has broadly classified breast cancer into four major molecular subtypes, as described by the St Gallen International Expert Panel, based upon the oestrogen receptor (ER), progesterone receptor (PR) and human epidermal growth factor receptor-2 (HER2Neu) status." (PMID 38414960, 2023). "Notably, the patient exhibited positive paraneoplastic antibodies and was diagnosed with estrogen receptor (ER)/progesterone receptor (PR) positive breast cancer, emphasizing the importance of excluding malignancy as a potential underlying cause." (PMID 37366475, 2023). "To confirm whether ASR-600 affects other pro-survival signaling pathways apart from AR in CRPC, we examined AKT, mTOR, Estrogen receptor (ER), and Progesterone receptor (PR) expressions in prostate and breast cancer cell lines." (PMID 36937838, 2023). "Thus, estrogen/progesterone receptor-positive breast cancers include the most common types of breast cancer (75% of all cases)." (PMID 37376065, 2023). "The level of PgR expression plays a vital role in guiding breast cancer treatment and prognosis." (PMID 37627192, 2023). "In breast cancer, the subtype determined by immunohistochemistry of estrogen receptor (ER), progesterone receptor (PgR), and human epidermal growth factor receptor type 2 (HER2) is one of the prognostic factors as well as a factor in the clinical stage, histological grade, and the marker Ki-67." (PMID 37163537, 2023). "Triple-negative breast cancer (TNBC) is a subtype of breast cancer in which the expression of estrogen receptor (ER), progesterone receptor (PR), and human epidermal growth factor receptor 2 (HER2) is negative, representing approximately 15%–20% of breast neoplasms." (PMID 37072408, 2023). "Further investigation in the stroma of breast cancer showed significant increases in RBMS3 expression in the specimens with positive expression of the progesterone receptor and samples with positive expression of the estrogen receptor (respectively, Mann–Whitney test p < 0.01 and p < 0.001)." (PMID 36769184, 2023). "However, it is unclear why the repressive effect of the progesterone receptor would outweigh, specifically at these genes, the many stimulatory mechanisms that promote the transcription of most other tRNA genes in breast cancers." (PMID 37509247, 2023). "Additionally, an analysis of the expression levels of Her2, estrogen receptor (Er), and progesterone receptor (Pr) of breast cancer patients showed that the Mix_Sub subtype was also marked by confusion in hormone levels in comparison to the other subtypes." (PMID 37064087, 2023). "In patients with HER2-positive breast cancer, tumor grade 3, estrogen receptor negativity, progesterone receptor negativity, strong HER2 positivity (score 3+), and the use of the neoadjuvant trastuzumab are associated with higher pathological complete response rates." (PMID 37871573, 2023). "Breast cancer has different molecular subtypes that are generally subcategorized based on the expression or lack of three cellular receptors, including estrogen receptor (ER), progesterone receptor (PR), and human epidermal growth factor receptor 2 (HER2)." (PMID 37009004, 2023). "Between East Asian and SEER patients, the status or rates of main breast cancer type, estrogen receptor, progesterone receptor, human epidermal growth factor receptor 2, breast subtype, and TNM stage were relatively close, and their differences were not statistically significant (P > .05)." (PMID 37505123, 2023). "Within the context of breast cancer diagnosis, standard evaluation involves classification according to the expression levels of key receptors such as estrogen receptor α (ER), progesterone receptor (PgR), and human epidermal growth factor receptor 2 (HER2)." (PMID 37627192, 2023).
breast cancer (continued). "NF1 associated breast cancer was more often oestrogen receptor negative, progesterone receptor negative and human epidermal growth factor receptor 2 (HER2) positive, which are all factors correlated with a poor prognosis." (PMID 36684394, 2023). "Firstly, the pathological analysis of samples was used to define the breast cancer receptor status as estrogen receptor (ER), progesterone receptor (PR), and human epidermal growth factor receptor 2 (HER2) positive (+) or negative (−), as well as the histological subtype of the tissue." (PMID 36527735, 2023). "In ERα-positive breast cancer, approximately half of the patients express PgR." (PMID 37627192, 2023). "DMBA-induced mammary cancer had been proved to be estrogen and progesterone receptor positive." (PMID 37056757, 2023). "Breast cancer is classified into three subtypes: the luminal subtypes that express estrogen receptor (ER) and progesterone receptor (PR), the human epidermal receptor 2 (HER2)-positive, and the triple-negative breast cancer (TNBC), which does not express any of the three receptors." (PMID 38028209, 2023). "The impact of progesterone receptor (PR) status on the prognosis of breast cancer after isolated locoregional recurrence (ILRR) remains unclear." (PMID 36869991, 2023). "Fortunately, after the finding of hormone receptors (HoR) including estrogen receptor (ER) and progesterone receptor (PR), endocrine therapy was gradually becoming the standard treatment for patients with HoR-positive breast cancer and significantly improved the survival for those patients." (PMID 36910652, 2023). "In clinical practice, immunohistochemistry‐based estrogen receptor (ER)/progesterone receptor (PgR)/human epidermal growth factor receptor 2 (HER2)/Ki67 examinations can be used to classify breast cancer based on four major subtypes, which are useful for treatment decision‐making." (PMID 36934442, 2023). "Our results suggest that predicting ESR1 and PGR gene expression from WSIs may potentially be a good method for differentiating ER and PR protein status in breast cancer patients." (PMID 37174035, 2023). "The correlation of RBMS3 expression with TNBC and the expression of progesterone receptor may also lead to the distinction of new molecular subtypes of breast cancer based on the analysis of combined biomarkers." (PMID 36769184, 2023). "There are different types of breast cancer, out of which 75% are hormone receptor–positive (HR-positive) breast cancer, that may be either estrogen receptor–positive (ER-positive) or progesterone receptor–positive." (PMID 37415453, 2023). "Triple-negative breast cancer (TNBC) is a subtype of breast cancer that lacks the expression of estrogen and progesterone receptor (ER/PR), as well as human epidermal growth factor receptor (HER-2), accounting for about 20% of the total diagnosed breast cancers in the world." (PMID 36902076, 2023). "Conversely, the most common type of breast cancer co-expresses ERα and PgR." (PMID 37627192, 2023). "A cohort study has shown that metformin use reduces the risk of luminal A breast cancer (estrogen/progesterone receptor positive, human epidermal growth factor receptor 2 negative) in postmenopausal patients with type 2 diabetes." (PMID 37179822, 2023). "In estrogen/progesterone receptor positive human breast cancer cell lines (MCF7) and estrogen receptor/progesterone receptor/human epidermal growth factor receptor 2 negative cell lines (MDA-MB-231), metformin has an inhibitory effect on mTORC1, which is an essential switch of tumor growth." (PMID 37179822, 2023). "In premenopausal women, obesity is associated with a lower risk of estrogens receptor positive (ER+) breast cancer and a higher risk of triple‐negative breast cancers (ER, progesterone receptor, PR, and human epidermal growth factor receptor 2 (HER2)." (PMID 37405618, 2023).
breast cancer (continued). "Furthermore, KYNU expression in breast cancer tissues was positively correlated with estrogen and progesterone receptor and negatively correlated with HER2 and Ki-67 expression, tumor size, and clinical stage." (PMID 37742026, 2023). "Approximately 70% of patients with breast cancer (BC) worldwide belong to the luminal subtype, including the hormone receptor (HR) [estrogen receptor (ER) and/or progesterone receptor (PgR)]-positive (HR+) and human epidermal growth factor (HER2)-negative (HER2−) subtypes." (PMID 37486454, 2023). "We showed the possible association of different DCs subpopulations expressing CD1a, cluster of differentiation 83 (CD83), CD123, DC-LAMP3 and DC-SIGN on their surface along with molecular subtypes of breast carcinoma, estrogen receptor (ER), progesterone receptor (PR) and progression-free survival." (PMID 37373062, 2023). "In addition, we investigated the correlation between YAP expression and the breast cancer molecular markers, including ERα, PR (progesterone receptor), and HER2 (human epidermal growth factor receptor 2)." (PMID 35654829, 2022). "An additional study found that two single-nucleotide polymorphisms (SNPs) (rs590688 and rs10895054) in the progesterone receptor gene were significantly associated with breast cancer in Black women, but not in white women." (PMID 35162279, 2022). "Breast cancer pathology molecules such as Ki-67, breast cancer molecular expression of estrogen receptor (ER), progesterone receptor (PR), and human epidermal growth factor receptor 2 (HER-2) are important markers to reflect the biological characteristics of breast tumor." (PMID 36249424, 2022). "However, Kunc and colleagues contended that patients with ER−/PgR + breast cancer would derive less benefit from the standard endocrine therapy than ER + /PgR + disease instead of chemotherapy." (PMID 35041101, 2022). "Similarly, patients with PgR− tumours were more likely to achieve pCR than those with PgR+ breast cancer (p < 0.001)." (PMID 35606616, 2022). "Triple-negative breast cancer (TNBC) presents an aggressive subtype of breast cancer with inferior survival outcomes, as it lacks molecular biomarkers such as estrogen receptor (ER), progesterone receptor (PR), and human epidermal growth factor receptor 2 (HER2)." (PMID 36559094, 2022). "PRMT1 interacts with the progesterone receptor in the nucleus of breast cancer cells." (PMID 35053470, 2022). "Currently, treatments for breast cancer are based on three broad classes: estrogen receptor α-positive or progesterone receptor-positive breast cancer, human epidermal growth factor receptor 2-enriched breast cancer, and triple-negative breast cancer that expresses none of these three receptors." (PMID 36059650, 2022). "Currently, the systemic individualized treatment of breast cancer is guided by molecular subtype, which was defined according to the expression status of estrogen receptor (ER), progesterone receptor (PR), human epidermal growth factor receptor 2 (HER2), and Ki-67." (PMID 35140303, 2022). "The panel consisted of both general cell structure markers such as Hoechst and Lamin for nuclear staining, as well as specific breast cancer subtype markers such as multiple cytokeratins, estrogen receptor, progesterone receptor, and human epidermal growth factor receptor 2 (HER2)." (PMID 36178966, 2022). "Given the genetic heterogeneity and aberrations in breast cancer, the clinically generalized standard for subtype distinction is based on the expression of estrogen receptor α (ERα), progesterone receptor (PR), and human epidermal growth factor receptor 2 (Her2)." (PMID 35847875, 2022). "The breast cancer was estrogen and progesterone receptor-positive." (PMID 36522673, 2022).
breast cancer (continued). "Although the mechanism of plasma D-dimer function in tumour development is still unclear, some studies have reported that elevated plasma D-dimer levels in breast cancer patients are associated with progesterone receptor expression, TNM staging and metastasis in breast cancer." (PMID 35337299, 2022). "Low TCL6 expression is linked to a poor prognosis, particularly in progesterone receptor-negative (PR) and luminal B breast cancer patients." (PMID 36207500, 2022). "Triple-negative breast cancer (TNBC), lacks the expression of estrogen receptor (ER) and progesterone-receptor (PgR) and amplification of human epidermal growth factor receptor 2 (HER2) gene, accounts for up to 20% of all breast cancers, and is associated with aggressive behavior and poor prognosis." (PMID 35821019, 2022). "In breast cancer, the discordance of estrogen receptor (ER), progesterone receptor (PR), and HER2 expression levels between matched primary and metastatic lesions could reflect temporal intratumor heterogeneity." (PMID 36010967, 2022). "In breast cancer, ER, PgR, and HER2 subtypes could be predicted, with AUCs of 0.82, 0.74, and 0.75, respectively." (PMID 36005456, 2022). "Worldwide, breast cancer, accounting for approximately 30% of cancers in women, can be divided into three subtypes based on estrogen receptor (ER), progesterone receptor (PR), and HER2 status: hormone receptor-positive, HER2-positive, and triple-negative breast cancer (TNBC)." (PMID 36225561, 2022). "Triple-negative breast cancer (TNBC) is a special type of breast cancer, which refers to the immunohistochemical examination of breast cancer cells showing that estrogen receptor (ER), progesterone receptor (PR), and human epidermal growth factor receptor 2 (HER2) all lack expression." (PMID 36556355, 2022). "Compared with traditional prognostic factors such as tumor size, lymph nodes, estrogen receptor (ER), and progesterone receptor (PR), molecular prognostic biomarkers show an obvious advantage in guiding clinical decision-making for managing breast cancer patients." (PMID 35265226, 2022). "Of note, PFOA was associated with the occurrence of estrogen receptor (ER)-, progesterone receptor (PR)-, and human epidermal growth factor receptor 2 (HER2)-positive breast cancer (ORER+ = 1.47, 95% CI: 1.19, 1.80; ORPR+ = 1.36, 95% CI: 1.09, 1.69; ORHER2 = 1.62, 95% CI: 1.19, 2.21)." (PMID 36085159, 2022). "NEO-201 was also observed to bind to 50% of breast cancer cell lines expressing either the estrogen receptor (ER) or the progesterone receptor (PR), whether alone or in combination with HER2 and to 75% of the HER2+ cell lines." (PMID 35804808, 2022). "Interestingly, this effect appeared to be driven by estrogen and particularly progesterone receptor positive breast cancers." (PMID 35189945, 2022). "Stage IV breast cancer has a high mortality rate and was afflicting our patient who was diagnosed with metastatic breast cancer estrogen receptor/progesterone receptor (ER/PR) positive, human epidermal growth factor receptor 2 (HER-2) neo negative, and low Ki-67." (PMID 35698681, 2022). "A 67-year-old woman was diagnosed with advanced breast cancer (mucinous carcinoma, histological grade I, estrogen receptor (ER) (−), progesterone receptor (PgR) (−), human epidermal growth factor receptor 2 (HER2) (1+), Ki-67 (20%), PD-L1 (IC1), cT4bN1M1 (PUL), and cStage IV)." (PMID 35800819, 2022). "Earlier studies demonstrated that FGFR4 overexpression may be a result of gene amplification, especially in breast cancer tumors with high lymph node metastases, as well as in estrogen receptor- and progesterone receptor-positive tumors." (PMID 36142417, 2022).
breast cancer (continued). "Interestingly, the overexpression of SAA1 resulted in decreased Akt activation in the estrogen and progesterone receptor positive breast cancer cell line (MCF7)." (PMID 36248994, 2022). "In addition, we observed a strong association with the survival of patients in the sub-group of luminal B tumors, a breast cancer molecular subtype characterized by positive ER and PGR status and a relatively unfavorable prognosis." (PMID 35996163, 2022). "Breast cancer is a heterogenous disease, which can be classified using gene and protein expression into basic subclasses based on the expression of estrogen receptor (ER), progesterone receptor (PR) and human epidermal growth factor receptor 2 (HER2)." (PMID 36139592, 2022). "Breast cancer is a heterogeneous entity, and the subtypes grouping could be basing on the expression status of progesterone receptor (PR), oestrogen receptor (ER), and human epidermal growth factor receptor 2 (HER2) in the tumors." (PMID 35614462, 2022). "Based on its receptor status, breast cancer can be classified into estrogen receptor (ER)-positive, progesterone receptor (PR)-positive, human epidermal receptor 2 (HER2)-amplified, and triple-negative breast cancer which is lack of the former three biomarkers." (PMID 35615146, 2022). "About 70% of breast cancers are estrogen receptor (ER) or progesterone receptor (PgR) positive." (PMID 36313626, 2022). "Thus, PgR status, like ER status, of breast cancer biopsy specimens is routinely assessed at diagnosis, typically by IHC, and is useful to guide therapy and inform prognosis." (PMID 35729608, 2022). "We present an unusual case of a Caucasian patient originally diagnosed with an estrogen receptor-positive, progesterone receptor-positive, and human epidermal growth factor receptor 2-negative primary breast cancer who had a recurrence after 15 years of therapy." (PMID 36510266, 2022). "BRCA1/2 mutation prevalence varied widely from 1.8% in sporadic breast cancer to 36.9% in estrogen receptor/progesterone receptor low HER2 negative breast cancer." (PMID 35681784, 2022). "Additionally, they showed that breast cancer patients with ER-/HER2+ tumors had shorter survival rates than those bearing ER+/PgR+/HER2- tumors." (PMID 35627114, 2022). "They suggested that estrogen receptor (ER) or progesterone receptor (PR) signaling could be a common factor in the development of thyroid cancer and breast cancer." (PMID 35207622, 2022). "Different breast cancer cells may have differences in the expression of estrogen receptor, progesterone receptor and HER2 protein." (PMID 35313846, 2022). "However, to date, the understanding of the clinical significance of ER and PgR status to HER2-positive breast cancer, especially regarding the HR-specific expression patterns, has been poorly investigated." (PMID 35041101, 2022). "Although the endocrine therapy is potent that the five-year breast cancer-specific survival could be over 99%, only 70% of breast cancer patients whose tumor cells overexpressed estrogen receptor or progesterone receptor proteins fit this therapy." (PMID 35799609, 2022). "Basal-like breast carcinomas, i.e., breast cancers showing triple-negative expression of estrogen receptor, progesterone receptor, and HER2 receptor, are among the most aggressive and deadly cancer subtypes, with a high metastatic ability associated with mesenchymal features." (PMID 36669020, 2022). "PGR (progesterone receptor) is usually overexpressed in breast carcinomas." (PMID 35625825, 2022). "In addition, hnRNPK transcripts are more abundant in ER- or progesterone receptor (PR)-positive breast cancer or luminal-type cancer." (PMID 33806648, 2021). "Triple negative breast cancer (TNBC) is an aggressive breast cancer subtype that lacks expression of targetable receptors maintained by other subtypes of the disease, including estrogen receptor (ER), progesterone receptor (PR) and human epidermal growth factor receptor-2 (HER2)." (PMID 34832904, 2021).